CD163 (CD163 molecule)
Description:
Acute phase-regulated receptor involved in clearance and endocytosis of hemoglobin/haptoglobin complexes by macrophages and may thereby protect tissues from free hemoglobin-mediated oxidative damage. May play a role in the uptake and recycling of iron, via endocytosis of hemoglobin/haptoglobin and subsequent breakdown of heme. Binds hemoglobin/haptoglobin complexes in a calcium-dependent and pH-dependent manner. Exhibits a higher affinity for complexes of hemoglobin and multimeric haptoglobin of HP*1F phenotype than for complexes of hemoglobin and dimeric haptoglobin of HP*1S phenotype. Induces a cascade of intracellular signals that involves tyrosine kinase-dependent calcium mobilization, inositol triphosphate production and secretion of IL6 and CSF1. Isoform 3 exhibits the higher capacity for ligand endocytosis and the more pronounced surface expression when expressed in cells. After shedding, the soluble form (sCD163) may play an anti-inflammatory role, and may be a valuable diagnostic parameter for monitoring macrophage activation in inflammatory conditions.
Synonyms: M130; MM130; SCARI1
Tractability: Small molecule: a structure with a bound ligand is known. Antibody: UniProt places it where antibodies can reach, with high confidence; its Gene Ontology location is reachable by antibodies, with high confidence; UniProt predicts a signal peptide or a membrane-spanning region; the Human Protein Atlas places it where antibodies can reach. PROTAC: its protein half-life has been measured.
Gene: Protein-coding gene on chromosome 12 (7,470,811 to 7,503,910, reverse strand). Ensembl gene ENSG00000177575.
Subcellular location: Secreted (Soluble CD163); Cell membrane
Subcellular location (Human Protein Atlas): Plasma membrane; Predicted to be secreted
Pathways (Reactome):
Disease: CD163 mediating an anti-inflammatory response
Vesicle-mediated transport: Scavenging of heme from plasma
Gene Ontology:
Molecular function: protein binding; scaffold protein binding; scavenger receptor activity
Biological process: vesicle-mediated transport
Cellular component: external side of plasma membrane; extracellular region; plasma membrane; cytosol; endocytic vesicle membrane; cytoplasm; membrane
Genetic constraint (gnomAD): Loss-of-function variants: 58 observed, 128.87 expected, observed/expected ratio (o/e) 0.45, 90% interval 0.36 to 0.56. The upper end of that interval is the gene's LOEUF score, 0.56, which puts it in group 2 of 6, group 1 being the genes least tolerant of losing a copy. Missense variants: 1,010 observed, 1,397.7 expected, observed/expected ratio (o/e) 0.72, 90% interval 0.69 to 0.76. Synonymous variants: 420 observed, 484.64 expected, observed/expected ratio (o/e) 0.87, 90% interval 0.8 to 0.94.
Homologues: Orthologues: chimpanzee CD163 (99% identical), macaque CD163 (96% identical), pig CD163 (84% identical), dog CD163 (83% identical), rat Cd163 (74% identical), mouse Cd163 (73% identical), guinea pig CD163 (72% identical), rabbit CD163 (71% identical). Paralogues in human: CD163L1 (55% identical), DMBT1 (34% identical), SCART1 (31% identical), SSC5D (26% identical), PRSS12 (20% identical), SSC4D (18% identical), LOXL2 (17% identical), LOXL4 (17% identical), LOXL3 (16% identical), CD6 (15% identical), CD5L (13% identical), CD5 (11% identical), and 3 more.
Diseases named in the same sentence as CD163 in open-access papers:
CD163 is named in the same sentence as 661 diseases in open-access papers, as found by Europe PMC text mining. Sharing a sentence is not in itself a finding about the gene and the disease. The quoted sentences say what the papers report.
breast carcinoma (184 papers, 2008 to 2026). "Although current literature supports the prognostic potential of CD163+ immune cells and associations to adverse clinicopathological features in primary breast cancer, the role of CD163+ immune cells in MBC is still unclear." (PMID 39751847, 2025). "Numerous studies have indicated that presence of CD163+ immune cells is associated with clinicopathological features and prognosis in a wide range of malignancies, including breast cancer." (PMID 39751847, 2025). "Consistent with our findings, a high incidence of CD163-positive macrophages in breast cancer was associated with earlier progression in several studies." (PMID 40510346, 2025). "Macrophages with CD68/CD163 double positivity are associated with poor prognosis of early-stage breast cancer, high-level histological grading, and high Ki67 expression." (PMID 41256322, 2025). "Regardless of the ER, PR, and HER2 status or the use of the HER2-targeted trastuzumab drug, the high count of M2 CD163+ TAM was associated with a poor outcome in HER2+ breast cancer patients." (PMID 40141437, 2025). "This is in line with a recent meta-analysis showing that high-CD163(+) TAMs are associated with poor patient clinical outcomes in several tumors including breast cancer." (PMID 40243442, 2025). "As the breast cancer subtype also has been proposed to associate with CD163, we next investigated the prognostic impact of CD163+ immune cells in the PT, stratified according to IHC-subtype as this was used to determine MBC treatment." (PMID 39751847, 2025). "Both High 2 and Basal groups had increased expression of macrophage inflammation markers CD68 and CD163, also associated with obesity, which correlates with poor prognosis in breast cancer." (PMID 40426890, 2025). "Only one study investigating specific immune cells reported that BMI changes since age 18 were associated with increased CD4 and CD163 levels in breast cancer." (PMID 39769193, 2024). "Foamy macrophages are also referred to as lipid-associated macrophages, and lipid-associated TAMs in breast cancer express an M2-like gene signature such as CD163 via the secretion of various protumor molecules." (PMID 37190178, 2023). "While the pan-macrophage marker CD68 has been mostly used to identify TAMs in breast cancer tissues in earlier studies, more recent studies have established that a high density of CD163+ TAMs in breast tumors is associated with poor prognosis." (PMID 35053472, 2022). "High amount of CD68+ and CD163+ TAMs was associated with lymph node metastasis, high Ki67 expression and poor prognosis in 1579 breast cancer patients from Zhejiang Provincial People’s Hospital and Zhejiang Tiantai People’s Hospital." (PMID 36686729, 2022). "There is also an increased incidence of CD68+ and CD163+ TAMs associated with breast cancer progression, including MAC387+ macrophages that are associated with viral infection." (PMID 35847899, 2022). "In tumors, CD163 promotes tumor development and is associated with worth prognosis in breast cancer, head and neck cancer, lymphoma and melanoma." (PMID 36686729, 2022). "Mounting evidence indicates that high levels of tumor-associated macrophages (TAMs), and especially CD163+ TAMs of the M2-like phenotype, are associated with poor prognosis in breast cancer." (PMID 35053472, 2022). "BMI change since age 18 was positively associated with novel CD4+ and CD163+ cell scores in breast cancer, supporting further study of the effect of modifiable factors like weight gain on the immune microenvironment." (PMID 36376974, 2022). "We and others have previously shown that CD163+ M2 macrophages are associated with poor prognosis in breast cancer." (PMID 34830923, 2021). "Tumour infiltration with CD163+ M2 macrophages is associated with features of aggressive disease and poor outcomes in breast cancer patients, notably those diagnosed with HER2 and basal subtypes." (PMID 33804486, 2021).
breast carcinoma (continued). "High CD163+ TAMs density was proven to be associated with poor prognostic parameters in breast cancer." (PMID 34577857, 2021). "Elevated CD163 expression has been associated with lower survival rates among various cancers, including breast cancer." (PMID 31937323, 2020). "In our earlier studies, we have demonstrated that CD163 expression in breast cancer cells is associated with advanced tumor stage and shorter disease-free survival but we have not observed an association with ILR." (PMID 30915533, 2019). "Consistent with the previous report, our comprehensive analysis found that basal-like breast cancer cells showed a strong association with TAMs, especially CD163-positive macrophages." (PMID 31528210, 2019). "Auvinen 9 reported that only CD163-positive macrophages were associated with tumor stage and nodal status in breast cancer." (PMID 31528210, 2019). "Macrophage traits, exemplified by CD163 expression, in tumor cells are associated with advanced stages and poor prognosis in breast cancer (BC)." (PMID 29725763, 2018). "As high cytotoxic T lymphocyte (CTL)/regulatory T cell (Treg) and high M1 (CD68+CD163-)/M2 macrophage ratios have been found to be associated with improved survival in breast cancer and cutaneous melanoma, respectively, we evaluated these ratios in our study." (PMID 28903377, 2017). "In the current study reported, the CD163+ TIMs (M2 macrophage phenotype) in both the primary breast cancer and metastatic ALNs were significantly associated with pCRs in malignant tissue following NAC." (PMID 28913366, 2017). "High levels of CD163+ TIMs in breast cancers were significantly associated with a GPR and pCR (p = 0.004, p = 0.008), respectively, following 8 cycles of NAC." (PMID 28913366, 2017). "CD163 was again associated with early distant recurrence in breast cancer, and with local recurrence in rectal cancer, and with reduced survival times in both." (PMID 26267609, 2015). "Cancer cells expressing CD163 were associated with poor prognosis in patients with breast cancer and rectal cancer." (PMID 24883329, 2014). "Macrophages are abundant in breast carcinoma and reports suggest that these TAMs (tumour associated macrophages) exhibit an alternatively activated (MΦ2-like) functional profile and are CD163 positive." (PMID 22028908, 2011). "It was stated that high densities of TAMs, particularly those expressing the CD163 marker, are associated with decreased overall survival and progression-free survival in breast cancer patients, with the prognostic impact varying by breast cancer subtype." (PMID 40933989, 2025). "Although the prognostic significance of TAMs in TCCRP remains undefined, the presence of a CD68+/CD163+ macrophage infiltrate, a signature associated with adverse features in broader breast cancer cohorts, was considered a potential high-risk factor in this individual case." (PMID 41256322, 2025). "In patients with primary breast cancer, significant associations have been made for high densities of CD163+ immune cells and higher tumor grade, larger tumor size, lymph node positivity, Ki67-positivity, hormone receptor negativity and/or triple negative/basal like subtypes." (PMID 39751847, 2025). "CD163+ immune cells are well-established players in the tumor microenvironment and several studies have reported associations with poor clinical features and outcome in primary breast cancer." (PMID 39751847, 2025). "However, high levels of CD163 GEX in synchronous LNM associated with shorter OS from the initial breast cancer diagnosis (P = 0.008, estimated median OS from PT diagnosis; 6.6 years, 4.3–8.9 95% CI versus 9.6 years 8.3–11.0 95% CI, respectively)." (PMID 39751847, 2025). "In addition, both high protein levels (IHC data) and GEX of CD163 in PT strongly associated with shorter survival from the time of the initial breast cancer diagnosis (PT diagnosis)." (PMID 39751847, 2025).
breast carcinoma (continued). "When we analyzed pro-tumor activity of TAMs using human breast cancer tissue, we verified that high expression of the macrophage marker CD163 was significantly associated with a reduced overall survival of these breast cancer patients in multiple breast cancer datasets." (PMID 39513934, 2024). "Moreover, a high density of CD163 was associated with poor outcomes in breast cancer in several studies." (PMID 38893266, 2024). "In the overall study population, CD163+ macrophage density was significantly associated with age (p = 0.025), breast cancer subtype (p < 0.001), stage (p < 0.001), grade (p < 0.001), and tumor size (p = 0.002); similar associations were observed when the Black population was examined separately." (PMID 38720366, 2024). "Our findings demonstrate that high PDLIM2 expression in breast cancer is predominantly associated with higher levels of CD163- and CD206-positive macrophages that likely represent the M2 subset, whereas the expression of T lymphocytic markers is not uniquely associated with PDLIM2 expression." (PMID 36531051, 2022). "Furthermore, none of the previously reported studies was focused on addressing the relationship between immunosuppressive CD163+ TAMs in patients with high-risk breast cancer who received chemotherapy." (PMID 35053472, 2022). "Another study reported that high levels of CD163+ TAMs within the subjectively selected most TAM-enriched breast cancer regions were significantly associated with aggressive features, such as vessel invasion and non-luminal molecular subgroups and reduced survival in a cohort of 282 patients." (PMID 35053472, 2022). "Methods to identify breast cancer patients with an elevated risk profile based on CD163+ TAM-centered tumor markers have the potential to improve clinical management of patients by identifying patients with unfavorable prognosis and opening the way for alternative tumor immune-boosting strategies." (PMID 35053472, 2022). "High infiltration of CD163+ TAMs are associated with poor survival in breast cancer patients." (PMID 35847899, 2022). "A 6-month weight loss intervention in breast cancer survivors who completed chemotherapy and/or radiation therapy led to changes in body weight and fat, serum levels of leptin and adiponectin, and breast tissue levels of CD163." (PMID 35256599, 2022). "In this study, we developed a novel method for objective phenotyping of CD163+ TAMs and present new spatial metrics of proximity of CD163+ TAMs to cancer cells that are independent predictors of clinical outcome in high-risk breast cancer patients treated with adjuvant chemotherapy." (PMID 35053472, 2022). "Furthermore, the infiltration of CD163+ TAMs seemed to be associated with specific molecular subtypes of breast cancer; since their numbers were found to be the highest in triple negative, and the lowest in ER+PR+ breast cancer samples." (PMID 34336660, 2021). "In addition, reduced recurrence-free survival was associated with increased stromal CD68+ CD163+ TAMs in basal-like breast cancer, and with increased tumor center CD68+ CD163+TAMs in colorectal cancer." (PMID 34988021, 2021). "Clinicopathological associations of MCT1&CD163 expression in breast cancer." (PMID 33178603, 2020). "Interestingly, we found that the expression of the tumor-associated macrophage (TAM) markers CD68 and CD163 was higher in HER-2-positive breast cancer." (PMID 32580398, 2020). "A high density of M1 macrophages expressing iNOS in the center of the tumor, together with high presence of CD8+ cells, has been associated with improved survival in HER2+ breast cancer; in contrast, the presence of CD163+ macrophages and T-reg cells was linked to poor prognosis." (PMID 33050070, 2020).
breast carcinoma (continued). "These in vitro studies were further substantiated in primary murine mammary tumor tissue, through the co-staining of F4/80 with the iron transporter, Fpn1, the expression of the M2 marker CD163, and the loss of intracellular iron stores within TAMs as identified by Perl’s Prussian Blue staining." (PMID 32708944, 2020). "Furthermore, we also performed a systematic review of published research to clarify the clinicopathological association and prognostic significance of CD68+ and CD163+ TAMs in early stage breast cancer." (PMID 31528210, 2019). "Two cases (2.4%), could not be evaluated for CD163-expression due to technical failure.CD163-expression > 15% was significantly associated with breast cancer-related death (p = 0.02)." (PMID 29725763, 2018). "Previous studies had confirmed that S100A7 expression could facilitate the infiltration of tumor-associated macrophages through multiple mechanisms in breast cancer, for example, it facilitated the infiltration of CD163-positive tumor-associated macrophages through activation of cPLA2." (PMID 38499391, 2024). "Likewise, overexpression of both MCT1 and CD163 by macrophages in the adjacent tissue may serve as a high-risk factor for poor prognosis in breast cancer patients." (PMID 33178603, 2020). "In breast cancer, CD163+ M2 TAMs are widely recognized as central drivers of the immunosuppressive microenvironment." (PMID 41426206, 2026). "In contrast, the long noncoding RNA NR_109 is strongly expressed in CD163+ TAMs in gastric and breast cancer tissues, where it activates c‐Myc transcription to promote M2 polarization." (PMID 41426206, 2026). "TAMs, especially those that take on an M2-like role (also called CD163), play a key part in suppressing the immune response in the breast cancer tumor environment." (PMID 41550427, 2025). "The aim of this study was to compare the expression of CD68, CD86, CD163 and PD-L1 in breast carcinomas and their paired brain metastases." (PMID 40510346, 2025). "In accordance with the associations to adverse clinicopathological features, high densities of CD163+ immune cells associate with poor OS, breast cancer specific survival (BCSS), and/or recurrence-free survival (RFS) in patients with primary breast cancer." (PMID 39751847, 2025). "Prior studies have shown that CD68+CD163+ macrophage infiltration, as well as CD68+CD163− macrophage presence in the TME, are associated with reduced overall survival in breast cancer patients." (PMID 40498004, 2025). "We aimed to evaluate the potential therapeutic responses and possible predictive value of double-positive (CD14 + CD16 +) monocytes and soluble CD163 (sCD163) in Egyptian breast cancer patients." (PMID 39955339, 2025). "The association between high levels of CD163 GEX and shorter survival was also validated in an independent dataset of patients with primary, early breast cancer." (PMID 39751847, 2025). "A meta-analysis of 8,496 breast cancer patients across 32 studies found that increased CD68+ and CD163+ TAM densities are significantly associated with decreased overall survival (HR= 1.7–2.5) and shorter disease-free survival (HR=1.8)." (PMID 41550427, 2025). "The current study revealed that a combination of GEN supplementation and moderate-intensity exercise increased the M1 macrophage marker CD68 while reducing M2 macrophage markers CD163 and Arg1 in breast cancer tissue." (PMID 40604704, 2025). "The CD8 infiltration decreased, whereas M2-like macrophage populations (CD163) increased along with LILRB4 in CRD-induced mammary tumors, as shown using MxIF." (PMID 41102383, 2025). "In the same line, in breast cancer it has been reported that CD163 expression is not only confined to macrophages but can also be expressed by cancer cells." (PMID 39451197, 2024). "Like in the case of breast cancer, the abundance of CD163+ TAMs was more predictive for overall and progression-free survival than of the CD68+ TAMs." (PMID 39451197, 2024).